EGFR (epidermal growth factor receptor)
Diseases named in the same sentence as EGFR in open-access papers (continued):
Sharing a sentence is not in itself a finding about the gene and the disease.
cancer (continued). "The chemical and genetic inhibition of EGFR and G9a revealed the significant role of the EGFR-G9a pathway in maintaining the cancer stemness property." (PMID 28787001, 2017). "The model does not include proliferation, which is an important element of seeding of metastases, although the authors discuss the role of EGFR in cancer progression." (PMID 28800767, 2017). "The EGFR up-regulated group (n = 412) were selected by the criterion that the average expression level of EGFR signaling up-regulation-responsive genes in cancer samples was ≧1.5X greater than that of normal samples." (PMID 28537886, 2017). "The sum of our knowledge from this vast array of research is allowing us to create even more effective drugs or drug combinations to target cancers with EGFR aberrations." (PMID 28513565, 2017). "ErbB2, a member of the ErbB family of receptor tyrosine kinases, triggers numerous oncogenic signals in cancer cells by binding other members of the family, such as Epidermal Growth Factor Receptor (EGFR) or ErbB3." (PMID 29285258, 2017). "Studies find that inhibition of EGFR phosphorylation alone is insufficient for generating a potent inhibitory response of cell proliferation in cancer cells." (PMID 29234489, 2017). "In fact, the combination of EGFR blockade and radiation exploits three distinct roles that the EGFR pathway plays in cancer progression: enhanced cell proliferation, the activation of pro-survival pathways, and DNA repair." (PMID 31093349, 2017). "Many intrinsic and iatrogenic cellular stresses such as UV-light, the cytokine TNFα or the cancer therapeutic cisplatin activate the EGFR in a tyrosine-kinase-independent way." (PMID 29176966, 2017). "Because of its pivotal role in cancer genesis and maintenance, the EGFR/RAS/RAF/MEK/ERK signaling cascade has been the subject of intensive research and pharmaceutical scrutiny to identify effective target‐based therapy for cancer treatment." (PMID 28306189, 2017). "The combined treatment of bortezomib and EGFR inhibitors has a synergistic growth inhibitory and pro-apoptotic activity in different human cancer cells and bortezomib inhibits the growth of gefitinib-resistant NSCLC cells." (PMID 29096687, 2017). "The toxicity of many of the newly developed targeted agents, including EGFR inhibitors, is a major concern for use in the adjuvant setting and particularly in primary cancer prevention." (PMID 29069801, 2017). "As our delivery system targets EGFR, a validated cancer marker, silencing of targets that can potentially synergize with EGFR inhibition is a possible application to be explored." (PMID 28641400, 2017). "EGFRvIIIpep belongs to EGFRvIII, a mutated form of the human epidermal growth factor receptor (EGFR), expressed on several tumors and associated with the expression of epithelial–mesenchymal transition and cancer stem cell genes." (PMID 29164053, 2017). "We previously reported that 111In-EGF-Au NP delivered a significant amount of radioactivity to EGFR-positive cancer cells in vitro, leading to radiotoxicity." (PMID 29071190, 2017). "Many cancer cells that first respond to TKIs and EGFR antibodies later acquire resistance by upregulating MEK and ERK signaling." (PMID 28513565, 2017). "We found that RPN2 silencing reduced glycosylation of EGFR, a highly N-link glycosylated cell surface glycoprotein that plays a critical role in majority of human cancers correlating with increased cell growth, proliferation, and differentiation." (PMID 29069815, 2017). "Gefitinib, a therapeutic for certain types of breast, lung, and other cancers, is a tyrosine kinase inhibitor that targets the ATP binding site in the cytoplasmic domain of EGFR." (PMID 28537895, 2017).
cancer (continued). "Even in patients with EGFR TKI-resistant cancer due to MET hyperactivation, EGFR signaling pathways remain active." (PMID 29140271, 2017). "The EGFR signaling pathway has been widely described to play a role in the pathogenesis of various cancer types including HNSCC." (PMID 28468237, 2017). "Thereby, EGFR activation stimulates proliferation, migration, angiogenesis, differentiation, survival, cancer formation and progression." (PMID 27683128, 2017). "These indicate that BCRP elevation is one of molecular mechanisms of c-MET/EGFR-induced cancer resistance." (PMID 29291022, 2017). "We conclude that PEG engagerEGFR can deliver PEGylated nanoparticles into cancer cells that express EGFR." (PMID 28593948, 2017). "In summary, we have developed radiolabelled PEGylated EGF-tagged Au NP for targeting EGFR-positive cancer." (PMID 29071190, 2017). "Oncogenic EGFR was reported to shed from cancer cells as cargo of membrane microvesicles, which can interacted with surfaces of other cells." (PMID 28402934, 2017). "Similar to erlotinib, Gefitinib is an EGFR inhibitor that inhibits signaling via EGFR in target cells, and is used for treating certain breast, lung, and other cancers." (PMID 28440691, 2017). "ATM (ataxia telangiectasia mutated) belongs to the PI3/PI4-kinase family, is able to form a complex with EGFR, causes phosphorylation of AKT and was suggested as a therapeutic target in cancer." (PMID 28199979, 2017). "Radionuclide molecular imaging is a potential method for in vivo measurement of EGFR expression in malignant tumours." (PMID 28729680, 2017). "PLA analysis of organotypic cancer rafts revealed an increase in EGFR-Nedd8, which is consistent with the known elevation of EGFR activity in HNSCC." (PMID 28891468, 2017). "The subsequent activation of the EGFR-AKT pathway leads to cancer cell proliferation, inhibits apoptosis, and enhances chemotherapy resistance." (PMID 28576144, 2017). "While radiation increases EGFR expression in cancer cells, blockade of EGFR signaling makes cancer cells more sensitive to radiation." (PMID 29254252, 2017). "HER3 activation is associated with resistance to several targeted cancer therapeutics including those targeting HER2 and EGFR." (PMID 28036286, 2017). "When combined with the ALK inhibitor, EGFR inhibitor gefitinib also showed an anti-cancer effect; however, the pan-HER inhibitor afatinib had a more potent effect on overcoming resistance, indicating the role of HER2 and HER3 activation in resistance." (PMID 28938595, 2017). "The California Cancer Consortium completed a phase II study of 37 patients with NSCLC and an EGFR mutation who had progressed on prior EGFR TKI therapy using the combination dose of 40 mg qd for cabozantinib and 150 mg qd for erlotinib." (PMID 28352985, 2017). "After cancer recurrence, the PD-L1 was further up-regulated in patients treated with chemotherapy or EGFR-TKI therapy but decreased in the patients with anti-PD1 therapy." (PMID 29254184, 2017). "Levels of p-AKT and p-ERK1/2 were also repressed in the shNRF2-SKOV3, which indicates lowered c-MET/EGFR downstream signaling in NRF2-silenced cancer cells." (PMID 29291022, 2017). "In three out of the five resistant patients, genetic mechanisms of resistance were lost in the absence of the continued selective pressure of EGFR inhibitor treatment, and these cancers were sensitive to a second round of treatment with EGFR inhibitors." (PMID 27757846, 2017). "The EGFR-specific Affibody molecule bound to and was taken up by EGFR-expressing A431 cancer cells in vitro, and in contrast to the natural ligand, EGF, the Affibody molecule did not activate EGFR signaling pathways." (PMID 28336959, 2017).
cancer (continued). "Since EGF and its receptor (EGFR) have been reported as an important signaling pathway leading to cancer, EGF was used to promote JB6 transformation." (PMID 28335476, 2017). "The aim of the present work was to define the efficacy of sequential treatment with first-, second- and third-generation EGFR-inhibitors and to investigate the potential role of Hh in the acquisition of cancer cell resistance." (PMID 28416737, 2017). "The GSEA results showed that EGFR signaling up-regulation-responsive genes were correlated with “miR-1 low” cancer samples." (PMID 28537886, 2017). "ErbB2-positive cancer cells largely depend on EGFR/ErbB2 signaling for their glucose uptake which was recently reported as a major factor in oncogenic KRAS pathway mutations." (PMID 28288164, 2017). "After further excluding 176 cancer samples containing both up- and down-regulated EGFR signaling gene signatures, the endogenous level of miR-1 in each group was calculated." (PMID 28537886, 2017). "EGFR mutant cancers are less responsive to single-agent PI3K/AKT inhibitors in comparison to HER2-amplified cancers and require the inhibition of both the PI3K and MEK pathways." (PMID 28446242, 2017). "Cancer cell lines dependent on known receptor tyrosine kinases (such as EGFR, ERBB2, c-MET, and FLT3) were found to be sensitive to SHP2 depletion." (PMID 29371942, 2017). "Epidermal growth factor receptor overexpression in human cancer can be effectively targeted by drugs acting as specific inhibitors of the receptor, like erlotinib, gefitinib, cetuximab and panitumumab." (PMID 28456787, 2017). "CD133 is known to regulate HIF-1α, and epidermal growth factor receptor (EGFR) mediated proliferation in cancer stem cells, although, its role in MSCs is not yet clear." (PMID 28884113, 2017). "Curiously, although both cancers upregulate PD-L1 in an EGFR-dependent fashion, two different signaling pathways were involved JAK/STAT and MAPK pathways." (PMID 28611673, 2017). "Our results show that EGFR-MBs are an effective and specific drug delivery system against cancer cells." (PMID 28938010, 2017). "It has also been demonstrated that blockade of EGFR results in a significant inhibition of the in vitro and in vivo growth of several cell lines derived from human carcinomas of various histological types." (PMID 28412732, 2017). "Binding of EGF to EGFR leads to the downregulation of FAK kinase activity in human carcinoma cells overexpressing EGFR." (PMID 28629170, 2017). "A superconducting ultrastrong 9T magnet reduced proliferation of CHO-EGFR cells (Chinese Hamster Ovary cells with EGFR overexpression) and EGFR-expressing cancer cell lines by ~35%, but minimally affected CHO cells." (PMID 27223425, 2016). "Although ligand-induced endocytosis was initially thought to be an important means to down-regulate cell surface EGFR, subsequent studies found that endocytic EGFR in cancer cells continues generating signals on endosomes that differ from on plasma membrane." (PMID 27034618, 2016). "EGFR targeting drugs can also eventually alter the EGFR downstream signaling pathway dependence in the cancer cells and reduce drug effectiveness, which is a phenomenon called secondary resistance." (PMID 26919318, 2016). "LeY can induce the activation of EGFR, and promote the migration of cancer cells by the glycosylation of EGFR; whereas anti-LeY antibody inactivated EGFR." (PMID 26636541, 2016). "Our EGFR phosphorylation data reveals a novel lateral signaling mechanism through which B6H12 inhibits proliferation of aggressive cancer cells." (PMID 26840086, 2016). "It is notable that cetuximab appears to be more effective than EGFR TKIs in cancers with ligand-dependent activation of EGFR, whereas TKIs are more effective in cancers with EGFR mutations." (PMID 27708224, 2016).
cancer (continued). "In summary, we reported that PA induced apoptosis and cell cycle arrest in A549 cancer cells in vitro and in vivo through blocking phosphorylation of EGFR pathways and activating JNK pathways for the first time to our knowledge." (PMID 27830146, 2016). "Previous in silico and in vitro studies confirmed the antitumor effect of NBPs on EGFR-driven cancers, albeit beside the EGFR itself the inhibition of RAS is seemed to be still another important target." (PMID 27780929, 2016). "In accordance, recent success using a combinational therapeutic approach inhibiting both, the EGFR-signaling and autophagy, has highlighted the nexus between the EGFR signaling and autophagy in regulating cancer cell survival and welfare." (PMID 30370422, 2016). "Researchers have tested a liposomal nanoparticle loaded with synthetic miRNA-34a mimics (MRX34) against cancer cells combined with the EGFR-TKI Erlotinib." (PMID 27895663, 2016). "Intrigued by these clinical observations, we exploited populations of cancer cells to study clonal evolution during EGFR blockade." (PMID 27929064, 2016). "The EGFR signaling pathway represents an important therapeutic target in various cancers e.g. in metastatic CRC." (PMID 27283768, 2016). "On the other hand, EGFR is involved in the UV signal transduction pathway leading to skin inflammation, photoaging, and cancer development." (PMID 27428951, 2016). "We modify the HaCaT keratinocyte cell line model to simulate cancer cells with constitutive activation of EGFR, HRAS, and PI3K in a controlled genetic background." (PMID 27650546, 2016). "Because EGFR is a potent activator of mitogenic and cell survival signaling, its overexpression in cancer is suggested to contribute to tumorigenesis, on the basis of which anti-EGFR therapies are being sought." (PMID 26728598, 2016). "The oral anti-cancer drugs that inhibit EGFR, gefitinib (Iressa) was the first EGFR TKIs used for solid tumor therapy and it had outstanding performance in the clinical treatment of the past." (PMID 27015267, 2016). "Epidermal growth factor receptor (EGFR) signaling has an important role in many cancers, as proliferation, differentiation and migration is mainly controlled by growth factors and their receptors." (PMID 26771644, 2016). "In accordance, early induction of autophagy has been documented in cancer cells subjected to anti- cancer treatment targeting growth-promoting signaling mechanisms including EGFR-signaling." (PMID 30370422, 2016). "Bio-functionalization of nanoparticles with EGF has been applied to specific targeting cancer cells, which overexpress EGFR and therefore, with ample interest for photothermal cancer treatment." (PMID 27788212, 2016). "Although the driver mutations including epidermal growth factor receptor (EGFR) and anaplastic lymphoma kinase (ALK) have revolutionized the treatment and prognosis of NSCLC, it just focused on the cancer cell intrinsic properties." (PMID 27153545, 2016). "EGFR is well established to contribute to resistance to cancer therapies and molecular targeting of the EGFR pathway can improve therapeutic outcomes to PDT and other types of treatment." (PMID 26784170, 2016). "Monoclonal antibodies, such as cetuximab that block EGFR signaling, have emerged as valuable molecular targeting agents in clinical cancer therapy." (PMID 27716204, 2016). "Among these, the epidermal growth factor receptor (EGFR) is a cell-surface molecule significantly involved in cancer development and progression; it can be processed into biological active soluble isoforms (sEGFR)." (PMID 27104520, 2016). "These transient increases probably represent release of nuclear DNA from cancer cells destroyed by the EGFR-TKI treatment." (PMID 27934896, 2016). "DNMT1, a negative regulator of CAGE, reduces cancer cell proliferation and migration by inhibiting EGFR-Akt signaling." (PMID 26863629, 2016).
cancer (continued). "Two important genes associated with lipid metabolism, gene expression and cancer were identified as DEGs between animals with high and low CLA-c9t11, specifically, epidermal growth factor receptor (EGFR) and RNPS." (PMID 27875996, 2016). "On the other hand, several EGFR antagonists are approved by the Federal Drug Administration (FDA) for the treatment of certain cancers." (PMID 27922822, 2016). "Other notable hub genes have also been claimed to be associated with cancers, including MAPK1, MAPK3, JAK2, EGFR, KRAS and NRAS." (PMID 27467251, 2016). "EGFR is a hot target for cancer therapy with many currently FDA approved drugs, and can activate at least 4 major downstream signalling cascades including; RAS-RAF-MEK-ERK, PI3 kinase-AKT, PLCgamma-PKC and STATs modules." (PMID 27438146, 2016). "One approach to improve EGFR-targeted therapy in cancers was combination with chemotherapy and radiation with variable success." (PMID 26909593, 2016). "PGRMC1 binds to EGFR and cytochromes P450, and is known to be involved in cancer proliferation and in drug resistance." (PMID 26988023, 2016). "Our immunohistochemical staining of liver tissues showed significant increase of Ki67, PCNA and EGFR expression in DEN-treated mice; treatment with sgp130 markedly decreased the staining of these cancer-associated biomarkers." (PMID 27080032, 2016). "Instead, EGFRvIII gains constitutive kinase activity, resulting in hyperactivation of EGFR signaling and enhanced proliferation and survival over cancers with EGFR alone." (PMID 27153091, 2016). "Further studies are warranted to clarify the impact of the anti-EGFR immune responses and EGFR-mediated immunomodulation for clinical application for cancer treatment." (PMID 27833557, 2016). "To further study the ability of Dsg2 to modulate the activation of EGFR and its relevance to cancer, we generated stable A431 SCC cells expressing a GFP-labeled Dsg2 (upper band)." (PMID 26918609, 2016). "Intracellular and receptor kinases, JAKs, EGFR and src, are hyper-activated in various cancers (including NSCLC), contributing to the phosphorylation of STAT3 at Tyr705." (PMID 26843613, 2016). "EGFR-null cells were unaffected, confirming the specificity of these immunotoxins toward EGFR-expressing cancers." (PMID 27153091, 2016). "One appropriate target is the Epidermal Growth Factor Receptor (EGFR), which is over-expressed in multiple types of human cancer and is usually associated with aggressive disease and low survival rate." (PMID 27598772, 2016). "Pathway analysis showed activation in the known cancer pathways, several inflammatory pathways and EGFR pathways." (PMID 27491308, 2016). "This study profiled genetic backgrounds of 83 patients with advanced NSCLC using a targeted pan-cancer NGS panel after they developed resistance to three different first generation EGFR TKIs." (PMID 27528220, 2016). "EGFR is one of the most important targets in current cancer research and its over-expression or abnormal activation often causes cell malignant transformation." (PMID 27527130, 2016). "Key significance of an overachieving Epidermal Growth Factor Receptor (EGFR)-signaling in cancer aggressiveness and poor prognosis is well recognized." (PMID 30370422, 2016). "For targeted NGS, the Accel-AmpliconTM 56G Oncology Panel covers hotspots of 56 cancer-related genes using 263 amplicons and the Accel-AmpliconTM EGFR Pathway Panel covers hotspots of EGFR, NRAS, KRAS and BRAF genes using 17 amplicons." (PMID 27589834, 2016). "The highest ranked among the most influential components were already explored as drug targets against cancer, including EGFR, PI3K, Raf, Ras, and Erk." (PMID 26904540, 2016). "EGF complexed to fluorescent photostable quantum dots by biotin-streptavidin system (bEGF-savQD) is attractive for both the basic research and therapeutic application such as targeted drug delivery in EGF-receptor (EGFR) expressing cancers." (PMID 26716513, 2016).